SLC4A11 (solute carrier family 4 member 11)
Diseases named in the same sentence as SLC4A11 in open-access papers (continued):
Sharing a sentence is not in itself a finding about the gene and the disease.
tumor (8 papers, 2017 to 2025). "A comparison of gene expression data in normal ovarian epithelial tissue and primary serous ovarian cancer revealed that among 10 family members, SLC4A11 expression was significantly upregulated in tumor tissue." (PMID 40563515, 2025). "Recent studies report elevated SLC4A11 protein levels in certain cancers, suggesting a potential role in tumor growth, particularly in glutamine-dependent cancers that rely on glutamine for proliferation." (PMID 40563515, 2025). "Recent research has also revealed high SLC4A11 protein expression in various cancers, suggesting a role in tumor growth and progression." (PMID 40563515, 2025). "SLC4A11 may support tumor progression through metabolic adaptation and mitochondrial and pH regulation." (PMID 40563515, 2025). "In the context of tumor growth and metastasis, the mechanisms and functions of SLC4A11 remain unclear and require further investigation." (PMID 40563515, 2025). "Since we established that SLC4A11 mediates intracellular ammonia transport in CSCs, we hypothesized that ammonia incorporates into metabolic pathways that contribute to tumor growth and that this effect is diminished with SLC4A11 depletion." (PMID 39287988, 2024). "Pseudotime related genes Msln and Slc4a11 can promote tumor progression." (PMID 36387251, 2022). "In addition, the high SLC4A11 expression group also had a higher ratio of tumor residual disease at the margin level of significance (p = 0.050)." (PMID 29091960, 2017). "Thus, SLC4A11 may also be involved in the process of tumor cell pH regulation, but this mechanism requires further investigation." (PMID 40563515, 2025). "Thus, SLC4A11 may mediate the mechanism of nitrogen metabolism rearrangement and promote tumor cell growth." (PMID 40563515, 2025). "In summary, we detected six DEGs (RIPK4, SCNN1A, SLC4A11, ELF3, CLDN4, and SOBP) which can serve as tumor markers for the diagnosis and prognosis of OC." (PMID 33742531, 2021). "We further investigated contexts of these spMOCA’s hub genes, where we identified specific prognostic genes serves as hub genes in the same tumor type, for example, WIPF2 and CASC3 for BRCA, COX6A1 and PRAP1 for CRC, E2F1 and AKR1C3 for LUSC, and TSPAN3 and SLC4A11 for OVCA." (PMID 41370198, 2025).
cancer (7 papers, 2017 to 2025). A tumor composed of atypical neoplastic, often pleomorphic cells that invade other tissues. "The SLC4A11 gene encodes a membrane transporter implicated in congenital hereditary endothelial dystrophy, Harboyan syndrome, and certain cancers." (PMID 40563515, 2025). "SLC4A11 is increasingly recognized as a prognostic marker due to its elevated expression and certain mutations in various cancers." (PMID 40563515, 2025). "Increased SLC4A11 expression is a component of some “glutamine-addicted” cancers, and is possibly linked to cells and tissues that rely on glutamine catabolism." (PMID 35053313, 2022). "We also discuss the emerging role of SLC4A11 in cancer metabolism and the common metabolic features of dystrophic corneas and tumors." (PMID 40563515, 2025). "SLC4A11’s involvement in pH regulation, lactate:H+ transport, glutaminolysis, and overexpression in certain cancers opens new avenues for exploring its function in glutamine-addicted cancers." (PMID 40563515, 2025). "There is a significant increase in SLC4A11 gene and SLC4A11 protein levels in cancer tissues compared to normal tissues as confirmed by quantitative PCR, immunocytochemical analysis, and Western blot analysis." (PMID 40563515, 2025). "In this review, we will often refer to corneal endothelial dysfunction related to SLC4A11, but also point out preliminary observations in auditory function, kidney, submandibular gland and in some carcinomas, in which there are emerging roles for SLC4A11." (PMID 35053313, 2022). "Given the pHi regulatory activity demonstrated in previous studies, SLC4A11 naturally owns a strong cellular buffering capacity that enables the highly glycolytic cancer cells to remove lactic acid rapidly." (PMID 29091960, 2017). "The precise substrates transported by SLC4A11 in cancer cells, whether NH3 directly or primarily H+/OH− ions activated by NH3, are not fully understood." (PMID 40563515, 2025). "Overall, we found that for three genes, GBP5, LINC00707 and SLC4A11, the BPA effect on the expression is substantially smaller compared to the effect observed as a consequence of cancer." (PMID 34062972, 2021).
genetic diseases (2 papers, 2013 to 2025). "Since SLC4A11-related inherited diseases primarily affect the corneal endothelium, its expression there has been extensively studied." (PMID 40563515, 2025). "We conclude that the corneal fluid accumulation found in genetic diseases of SLC4A11 arises at least in part from defective water movement by SLC4A11." (PMID 23813972, 2013).
eye disorder (1 paper, 2007). A non-neoplastic or neoplastic disorder that affects the eye. "The autosomal recessive form of congenital hereditary endothelial dystrophy (CHED2) is a rare eye disorder caused by mutations in the SLC4A11 gene located at the CHED2 locus on chromosome 20p13-p12." (PMID 17262014, 2007).
SLC4A11 also shares sentences with these, for which no sentence is quoted: hearing defects (2 papers); posterior polymorphous corneal dystrophy (2); angiosarcoma (1); cognitive decline (1); colon cancer (1); connective tissue diseases (1); dementia (1); epilepsy (1); Fuchs corneal endothelial dystrophy type 4 (1); gelatinous drop-like corneal dystrophy (1); Huntington disease (1); infection (1); Nystagmus (1); serous carcinoma (1); squamous cell carcinoma of the lung (1); uterine corpus endometrial carcinoma (1); virus infection (1).